TTN (titin)
Diseases named in the same sentence as TTN in open-access papers (continued):
Sharing a sentence is not in itself a finding about the gene and the disease.
muscular dystrophy (continued). "One uniquely useful model to unravel titin’s functions, muscular dystrophy with myositis (mdm), arose spontaneously in mice as a transposon-like LINE repeat insertion that results in a small deletion in the N2A region of titin." (PMID 32492876, 2020). "Of note, the proteins encoded by genes linked to other muscular dystrophies such as COL6A1, CAV3, DYSF, DMD, TTN, and VCP and the strongest family sequencing candidates INTS1 and ANK2 were all found in nuclear envelope proteomics datasets." (PMID 31862442, 2020). "The results further support a model in which N2A – actin binding in active muscle increases titin stiffness, and that impairment of this mechanism contributes to the phenotype in muscular dystrophy with myositis." (PMID 30275509, 2018). "A loss or a disruption of sarcomeres and their passive elastic proteins, such as titin, α-actinin, and nebulin, or myofibrillar remodelling in hampered regeneration cycles as in muscular dystrophy, could provide an explanation." (PMID 38672689, 2024). "Muscular dystrophy with myositis (mdm) is one such disease caused by a LINE repeat insertion, leading to exon skipping and an 83-amino acid residue deletion in the N2A-PEVK region of mouse titin." (PMID 36115951, 2022). "In addition, some of the genes recently found to be associated with ARVC are also responsible for myopathies/muscular dystrophies, such as DES, LDB3, and TTN." (PMID 28750076, 2017). "Due to the presence of titin in both skeletal and cardiac muscle, measurement of the marker in other pathologies such as muscular dystrophies could indicate a broader use for this marker." (PMID 22768802, 2012). "Pathways related to muscular dystrophy—primarily involving CAV3 and TTN—demonstrated moderate enrichment (p ≈ 10−4)." (PMID 41153379, 2025).
hypertrophic cardiomyopathy (36 papers, 2012 to 2025). "There are four critical TTN mutations linked to familial hypertrophic cardiomyopathy (HCM; MIM #613765), a condition that stands as the leading cause of sudden cardiac death among young adults." (PMID 41190030, 2025). "Among the genes implicated in non-hypertrophic cardiomyopathies, Titin has consistently been identified as the most common one." (PMID 41329234, 2025). "Mutations in this gene might be associated with familial hypertrophic cardiomyopathy nine and/or the production of autoantibodies against Titin, especially in Scleroderma." (PMID 37372431, 2023). "This study aimed to explore the early diagnosis of abnormal left ventricular systolic function of rare pathogenic titin (TTN) mutation gene carriers in familial hypertrophic cardiomyopathy (FHCM) by three-dimensional speckle tracking echocardiography (3D-STE) combined with gene detection." (PMID 36304977, 2022). "TTN was known as a gene associated with familial hypertrophic cardiomyopathy." (PMID 34761007, 2021). "For example, TCAP (regulates sarcomere assembly and titin assembly; implicated in familial hypertrophic cardiomyopathy), MYL3 (myosin light chain 3; implicated in left ventricular hypertrophic cardiomyopathy and restrictive cardiomyopathy), LDB3, and DES were highly downregulated." (PMID 34338636, 2021). "Additionally, TTN is implicated in hypertrophic cardiomyopathy (HCM)." (PMID 41190030, 2025). "Isolated case reports and small series have suggested a possible association between TTN missense variants and arrhythmogenic right ventricular cardiomyopathy (ARVC), hypertrophic cardiomyopathy (HCM) and restrictive cardiomyopathy." (PMID 41329234, 2025). "Whereas TTN truncations are common in DCM, there is evidence that TTN truncations are rare in the hypertrophic cardiomyopathy (HCM) phenotype." (PMID 27493940, 2016). "Titin (TTN) is a muscle protein that is critical in hypertrophic cardiomyopathy." (PMID 37499109, 2023). "“Hypertrophic cardiomyopathy” in the signal pathway was followed with the p.adjust value of 1.10×10-3 and the corresponding collective action gene set with mutations included 8 genes: IGF1, CACNA1S, MYH7, IL6, TTN, CACNB2, LAMA2, DMD." (PMID 37876543, 2023). "Due to the relatively low number of detected down-regulated genes, only one pathway was found to be significant, and it contained genes overexpressed at the start of the training schedule (T1): hypertrophic cardiomyopathy (HCM) pathway (CACNB1, TPM1, TPM2, TTN)." (PMID 28381206, 2017). "Recent reports indicated that around eighty circRNAs were expressed from the titin gene and that the expression of some of these circRNAs is dynamically regulated in DCM but not in hypertrophic cardiomyopathy (HCM)." (PMID 29304022, 2018). "Previously, and in hypertrophic cardiomyopathy (HCM) patients, we provided evidence on the oxidative stress-related alterations in titin-based myocardial stiffness, as anticipated from the increased titin S-glutathionylation and ubiquitination compared to human–nonfailing control." (PMID 36358581, 2022).
myasthenia gravis (29 papers, 2012 to 2025). Myasthenia gravis (MG) is a rare, clinically heterogeneous, autoimmune disorder of the neuromuscular junction characterized by fatigable weakness of voluntary muscles. "Anti-titin autoantibodies are frequently found in myasthenia gravis, in association with RACh Ab, mostly in a context of thymic abnormalities." (PMID 40757701, 2024). "Anti-striated muscle antibodies include anti-titin antibodies and anti-Kv1.4 antibodies, and are often found in patients with thymoma-associated myasthenia gravis, suggesting an overlap in the pathophysiology between ICI-induced myositis and myasthenia gravis." (PMID 36982715, 2023). "Whether this decreased expression promotes a breakdown in T cell tolerance against Titin and increased susceptibility to myasthenia gravis warrants further investigation." (PMID 40625741, 2025). "Moreover, anti-titin antibodies have been found in a subset of patients with myasthenia gravis, a neuromuscular junction disease that is mostly associated with autoimmune antibodies, such as anti-acetylcholine receptor antibody." (PMID 37601060, 2023). "Moreover, anti-titin antibodies have been found in a subset of patients with myasthenia gravis, a neuromuscular junction disease that is mostly associated with autoimmune antibodies, such as the anti-acetylcholine receptor antibody." (PMID 37601060, 2023). "As we know, although RyR and titin antibodies are rare in myasthenia gravis patients, they can help in recognizing affected individuals but are not sufficient as separate diagnosis indicators." (PMID 39968461, 2025). "Myasthenia gravis with anti-titin Abs only seems to be more frequently responsible for respiratory involvement and is less responsive to conventional therapy." (PMID 40757701, 2024). "The co-existence of myasthenia gravis and autoimmune hepatitis is rare, and a cohort of patients with myasthenia gravis anti-titin antibodies seems to be highly relevant." (PMID 37601060, 2023). "For example, thymomas that are associated with myasthenia gravis (MG) overexpress the mid-sized neurofilament gene (NEF), which shares sequences coding for acetylcholine receptors and titin epitopes that are associated with MG." (PMID 35565190, 2022). "This study aimed to summarize the clinical characteristics and prognosis of patients with anti- acetylcholine receptor (AChR) positive myasthenia gravis (MG) with a combination of anti-LRP4 or Titin antibodies." (PMID 35614931, 2022). "AChR antibodies (17.0 nmol/L, RF < 0.4) and titin antibodies were positive and repetitive nerve stimulation showed an abnormal decrement matching the criteria of myasthenia gravis." (PMID 30107838, 2018). "The diagnosis of concurrent myositis and myasthenia gravis, especially in the presence of ryanodine receptor and titin antibodies, should lead neurologists to adopt different treatment strategies compared to those applied in myasthenia or myositis alone." (PMID 27623618, 2016). "While nearly 90% of myasthenia gravis patients have autoantibodies targeting AChR and/or the muscle-specific tyrosine kinase (MuSK), other autoantibodies targeting striated muscles, particularly the sarcomere protein Titin, have been detected in some myasthenia gravis patients." (PMID 40625741, 2025). "In contrast, genes coding for the acetylcholine receptor (CHRNA1), the muscle antigen titin (TTN), and MUSK, which are associated with the neuromuscular autoimmune disease myasthenia gravis, were predominantly found in the myoid, neuroendocrine, and ciliated subsets." (PMID 33597545, 2021). "This study aimed to investigate the clinical characteristics of patients with myasthenia gravis (MG) who are double-seropositive for acetylcholine receptor antibodies (AChR-Ab+) and titin antibodies (Titin-Ab+)." (PMID 41393996, 2025).
myasthenia gravis (continued). "The co-existence of myasthenia gravis and autoimmune hepatitis is rare, and in a cohort of patients with myasthenia gravis anti-titin antibodies seem to be relevant to autoimmunity in consideration of these data and the number of patients who may not be symptomatic." (PMID 37601060, 2023). "According to the generalized criteria for myasthenia gravis, the presence of RyR or titin antibodies alone is typically not enough to confirm a diagnosis of myasthenia gravis." (PMID 39968461, 2025). "Anti-Titin autoantibodies have been detected in a significant (80%) number of patients with thymomatous myasthenia gravis, while they are present only in a minority of myasthenia gravis patients without thymoma." (PMID 40625741, 2025). "Although a diagnostic workup found several autoantibodies against double-stranded deoxyribonucleic acid (dsDNA), acetylcholine receptor (AChR), and titin in his serum, no clinical evidence of systemic lupus erythematosus (SLE) or myasthenia gravis (MG) was observed." (PMID 40995362, 2025). "Fifth, this study measured only the concentrations of AchR-Ab in all patients with MG but did not measure other myasthenia gravis-related antibodies, such as anti-MuSK antibodies, anti-LRP4 antibodies, anti-titin, and anti-RyR antibodies, in all the patients." (PMID 35265719, 2022).
breast carcinoma (28 papers, 2015 to 2025). "High TTN mRNA levels correlate with improved disease-free survival in HER2 + breast cancer, our data revealed low TTN expression in 68% of TNBCs and is associated with enhanced metastasis." (PMID 41326912, 2025). "TTN is one of the most commonly mutated genes in solid tumors, such as gastric cancer tumors, and other tumor types such as lung cancer, breast cancer, and colon cancer." (PMID 39337369, 2024). "A high mutation frequency for MUC17 and TTN have recently been reported as an unexpected finding in a study of early onset breast cancer (EOBC) in Taiwanese women." (PMID 39723380, 2024). "TTN has also been reported to be mutated frequently in many types of tumors such as breast cancer, lung squamous cell carcinoma, lung adenocarcinoma, and colon adenocarcinoma." (PMID 34746153, 2021). "Using per-cancer and pan-cancer settings, the model predicted both known, including EGFR inhibitors in non-small cell lung cancer and tamoxifen in ER+ breast cancer, and novel drug targets, such as vinorelbine for TTN-mutated tumors." (PMID 30704458, 2019). "From the list of identified driver genes, titin (TTN) gene is one of the important genes with an average of 15.78% mutation rate in breast cancer while earlier studies also revealed that TTN is highly mutated in other cancers." (PMID 28477017, 2017). "The use of TTN as a good predictable factor for chemotherapy in breast cancer should be considered after revealing the role and clinical significance of TTN mutation in breast cancer in further studies." (PMID 38424522, 2024). "Thus, the role of MUC17 and TTN should further be investigated on how mutations in them may relate to early onset of breast cancer in Kenyan patients." (PMID 39723380, 2024). "This is reflective of breast cancer associations reported in the literature [KMT2C:, DMD:, TTN:, RYR2:]." (PMID 40685627, 2025). "The opposite is true for other genes, like TTN, MUC4 and RYR2, which are amongst the most frequently mutated genes in breast cancer, but were clearly deprioritized by SomInaClust." (PMID 25903787, 2015). "Additionally, studies have reported changes in the expression of titin in breast cancer tissues that contributed to the invasive characteristics of breast cancer cells." (PMID 39944242, 2025). "Exploring the downregulated expression of titin in OC holds potential preventive interventions, which may also lead to vaccine development for OC and potentially other cancers such as breast cancer." (PMID 39944242, 2025).
breast carcinoma (continued). "BeME-WithFun also uncovered the same TTN and mucin modules as in the case of breast cancer." (PMID 29023534, 2017). "TTN mutations in breast cancer have not shown a strong discriminatory effect on patient survival." (PMID 32670437, 2020). "Based on the TCGA data, the most frequently altered gene in breast cancer was KMT2C (12%), and the TTN gene (17%) in ovarian cancer." (PMID 35893033, 2022).
lung carcinoma (24 papers, 2014 to 2025). "In lung cancer, several recent studies reported that TTN mutations enhanced anti-tumor immunity and were associated with favorable responses to ICI administration." (PMID 36653483, 2023). "For example, TTN, one of the largest genes in the genome, is known to have a very high mutation rate in lung cancer." (PMID 26047463, 2015). "This is consistent with results from COSMIC that 244 out of the 467 (52%) lung cancer samples sequenced have somatic mutations in TTN." (PMID 25112956, 2014). "Furthermore, lung cancer patients with titin mutations also had a more favorable overall survival and a good chemotherapy response compared to patients with wild-type titin." (PMID 39944242, 2025). "TTN mutation has been reported to be correlated with prognosis in lung cancer and gastric cancer." (PMID 34306002, 2021). "TTN mutation was identified as a predictor of improved objective response rate to immune checkpoint blockade immunotherapy in seven public clinical cohorts, including advanced cases of cutaneous squamous cell carcinoma, stomach adenocarcinoma, skin cutaneous melanoma, and lung cancer." (PMID 35095878, 2021). "Lung cancer is one of the many tumor forms that frequently have mutations in TTN, the longest-known gene producing the TITIN protein." (PMID 40661938, 2025). "What is more, other mutated genes, such as TTN, MUC16, and RYR2, all previously reported to regulate tumorigenesis and chemoresistance in lung cancer, were the most common mutations in both cohorts, indicating a lack of significant immune infiltration." (PMID 36246963, 2022). "Western blotting analysis demonstrated that five lung cancer cell samples had significantly decreased expression of titin, compared with normal alveolar epithelial cell sample." (PMID 35875159, 2022). "The results showed that HTR3C mRNA levels were positively correlated with TTN mRNA levels in lung cancer tissues." (PMID 34868311, 2021). "A study delineated that the TTN mutant may be a potential predictor in using immune checkpoint inhibitors in lung cancer patients." (PMID 37147453, 2023). "It has been reported that TTN/ZFHX4 missense triggered the development of tumor-associated antigens and could predict a good prognosis in lung cancer." (PMID 35178154, 2022). "mRNA expression of TTN was significantly lower in lung cancer." (PMID 35875159, 2022). "However, whether TTN is involved in lung cancer development is controversial." (PMID 36685819, 2022). "The lncRNA Titin antisense RNA 1 (TTN-AS1) is transcribed from the opposite strand of the Titin (TTN) gene, and its overexpression correlates with poor prognosis in multiple cancers, including breast cancer, lung cancer, and reproductive system cancers." (PMID 34606420, 2021). "On the other hand, TTN and/or MUC16 were still retained in the top 10 for some cancers such as large intestine and lung cancers, suggesting their tumorigenic relevance to these cancers." (PMID 26212640, 2015).